MPO (myeloperoxidase)
Diseases named in the same sentence as MPO in open-access papers (continued):
Sharing a sentence is not in itself a finding about the gene and the disease.
lung adenocarcinoma (3 papers, 2021 to 2023). A carcinoma that arises from the lung and is characterized by the presence of malignant glandular epithelial cells. "We exposed human lung adenocarcinoma cells (A549 cells) to different concentrations of MPO and assessed the effects of the enzyme on cell proliferation." (PMID 37627581, 2023). "Using the lung adenocarcinoma cell line A549, we showed that MPO promotes cancer cell proliferation while protecting cells from apoptosis." (PMID 37627581, 2023). "MPO-positive neutrophils were quantified in tumour blocks from lung adenocarcinoma (n = 48) and control tissue (n = 20) by IHC." (PMID 34203378, 2021). "The copy numbers of both the target (CYP2C8, CYP3A4) and the reference genes (ALB, B2M, BCKDHA, F5, CD36, MPO, TBP, RPPH1) established in primary lung adenocarcinoma by the qPCR-based method were congruent with those determined by next-generation sequencing (for 10 genes, slope = 0.9498, r2 = 0.72)." (PMID 37686184, 2023).
metastatic colorectal cancer (3 papers, 2022 to 2023). "We recently demonstrated the association of MPO and NE concentrations with the amounts of cirDNA and anti-cardiolipin auto-antibodies in a large cohort (N = 217) of newly diagnosed metastatic colorectal cancer (mCRC) patients." (PMID 36443816, 2022). "Higher levels of intratumor NETs and preoperative serum MPO-DNA as a marker of NETs were correlated with shorter survival in metastatic colorectal cancer." (PMID 36859358, 2023). "In a recent study, researchers were able to distinguish between patients with metastatic colorectal cancer and healthy individuals based on cfDNA, MPO, and neutrophil elastase (NE) concentrations." (PMID 36140548, 2022). "It was further suggested that cfDNA levels, in combination with MPO-DNA and NE, could serve as potential biomarkers for disease severity, prognosis or treatment guidance of metastatic colorectal cancer and cancer in general." (PMID 36140548, 2022).
mixed connective tissue disease (3 papers, 2013 to 2024). Mixed connective tissue disease (MCTD) is a rare autoimmune disorder that is characterized by features commonly seen in three different connective tissue disorders: systemic lupus erythematosus, scleroderma, and polymyositis. "A woman diagnosed with mixed connective tissue disease (MCTD) developed an anti-myeloperoxidase (MPO) antineutrophil cytoplasmic antibody (ANCA) and nephrotic syndrome with normal serum creatinine." (PMID 23864923, 2013).
Myalgia (3 papers, 2012 to 2023). "First, our study indicated that fever was more common, and the proportion of fever and myalgia in the MPO-ANCA–positive group was significantly higher than that in the ANCA-negative group." (PMID 35833130, 2022). "In our study, the patients with positive MPO-ANCA suffered more fever and myalgia and had higher ESR, CRP, and BVAS, suggesting MPO-ANCA as an inflammatory mediator." (PMID 35833130, 2022). "Compared with the ANCA-negative group, the MPO-ANCA–positive group had higher percentages of patients with fever (84.0% vs. 40.9%, p = 0.0001) and myalgia (40.0% vs. 17.2%, p = 0.02)." (PMID 35833130, 2022). "Generally, patients with positive MPO-ANCA have a more active disease with higher CRP levels, higher ratios of fever and myalgia, and significantly more common rhinosinusitis than those with negative MPO-ANCA." (PMID 37215720, 2023).
myeloproliferative neoplasm (3 papers, 2019 to 2023). A clonal hematopoietic stem cell disorder, characterized by proliferation in the bone marrow of one or more of the myeloid (i.e., granulocytic, erythroid, megakaryocytic, and mast cell) lineages. "The elevated circulating levels of MPO-DNA was also associated with thrombosis in patients with myeloproliferative neoplasms (MPN)." (PMID 38067137, 2023).
myocarditis (3 papers, 2013 to 2025). Myocarditis is a condition that is characterized by inflammation of the heart muscle (myocardium). "MPO is a biomarker of myocardial damage, and its activity andexpression levels are heightened in patients with myocarditis." (PMID 40927089, 2025). "NETs are network structures containing DNA, histone, MPO, NE, and cathepsin G.Under myocarditis conditions, neutrophils recruited to the site of inflammationtrigger the release of NETs via reticular tissue proliferation in a novel form ofprogrammed cell death termed NETosis." (PMID 40927089, 2025). "Therefore, in the pathogenesis ofmyocarditis, the content of MPO and NE can indirectly reflect the progression ofmyocarditis and provide auxiliary means for the examination of myocarditis." (PMID 40927089, 2025). "In parallel, myocardial inflammation was induced via nitric oxide production, neutrophil accumulation (myeloperoxidase activity) and activation of the p38-mitogen-activated protein kinase pathway resulting in cytokine release (tumor necrosis factor-alpha, interleukin-6) in control vs. sham animals." (PMID 23663695, 2013). "Therefore, an elevated MPO level in blood tests may indicateinflammatory activity and contribute to the diagnosis of myocarditis." (PMID 40927089, 2025). "Interestingly, myocarditis in this group was observed as frequently as in ANCA-negative patients and more frequently than in MPO-ANCA patients." (PMID 37215720, 2023).
nephrotic syndrome (3 papers, 2013 to 2025). A collection of symptoms that include severe edema, proteinuria, and hypoalbuminemia; it is indicative of renal dysfunction. "One patient (patient 6) had a past history of nephrotic syndrome due to class V LN, 17 years before the occurrence of rapidly progressive GN with IAH, which led to a diagnosis of MPO-associated AAV with pauci-immune GN." (PMID 27258503, 2016).
neuroblastoma (3 papers, 2016 to 2020). Neuroblastoma (NB) is the most common solid, extracranial childhood tumor. "For example, in the previous experiments with human lung epithelial Calu-3 cells, mouse neuroblastoma Neuro2a cells, mouse pancreatic β Min6 cells, and human aortic endothelial cells, the cells were incubated with MPO for 1 h prior to the addition of GO to initiate the formation of H2O2." (PMID 33321763, 2020).
non-small cell lung carcinoma (3 papers, 2013 to 2024). A group of at least three distinct histological types of lung cancer, including non-small cell squamous cell carcinoma, adenocarcinoma, and large cell carcinoma. "Lesion volume and maximum diameter had the highest predictive performance in response to treatment with Gefitinib for non-small-cell lung carcinoma patients, which indicated that the range and median of the lesion can predict treatment resistance for those MPO-AAV patients with lung involvement." (PMID 37503353, 2023).
pericardial effusion (3 papers, 2019 to 2025). Fluid collection within the pericardial sac, usually due to inflammation. "Over the course of therapy, he developed systemic vasculitic features, including migratory arthritis and pericardial effusion, with laboratory evidence of high p-ANCA titres and MPO positivity, confirming PTU-induced ANCA-associated vasculitis." (PMID 41393668, 2025).
peripheral artery disease (3 papers, 2018 to 2023). "In the context of peripheral artery disease, high MPO has been associated with poorer outcomes and suggested as a biomarker for risk stratification." (PMID 38137627, 2023).
pneumococcal meningitis (3 papers, 2019 to 2025). An acute purulent infection of the meninges and subarachnoid space caused by Streptococcus pneumoniae, most prevalent in children and adults over the age of 60. "The high 3Cl-Tyr/p-Tyr ratio in pneumococcal meningitis suggests robust inflammation because 3Cl-Tyr is a marker of MPO activation and, indirectly, of inflammation." (PMID 31581487, 2019). "Analysis of cerebrospinal fluid (CSF) from humans and rodents with pneumococcal meningitis reveals the presence of neutrophils and externalized neutrophil proteins such as myeloperoxidase (MPO), histones, NE, and proteinase 3 (PR3), which may imply NET production." (PMID 36873885, 2023).
polycystic ovary syndrome (3 papers, 2016 to 2023). A disorder that manifests as multiple cysts on the ovaries. "Recent research has found a connection between IR with increased MPO production in leucocytes and enhanced ROS formation in polycystic ovary syndrome (PCOS) patients, emphasizing MPO's role in oxidative stress events." (PMID 35783193, 2022).
pulmonary tuberculosis (3 papers, 2017 to 2024). A bacterial infection that affects the lungs and is caused by Mycobacterium tuberculosis. "In patients with pulmonary tuberculosis, 2.9-25% by indirect immunofluorescence and 0-75% by enzyme-linked immunosorbent assay have been reported to be positive for MPO-ANCA." (PMID 39569301, 2024). "When only the individuals with pulmonary TB were compared to those with ORD, significant differences were observed for SAA, CRP, VEGFR3, RANTES, Pentraxin3, Ferritin, CCL18, MPO, GDF-15, MMP-1, PDGF-BB, Procalcitonin, MDC, Myoglobin, and VCAM-1." (PMID 33732236, 2021).
pustular psoriasis (3 papers, 2021 to 2024). "Although the relationship between MPO deficiency and pustular psoriasis was first described in 1996 in an individual case report, it was only recently that a mutation in MPO gene was recognized as a background for GPP." (PMID 34445754, 2021). "Mutations in MPO genes causing MPO deficiency, found in cases of pustular psoriasis, may lead to increased activity of neutrophilic proteases." (PMID 37628670, 2023). "On the other hand, MPO mutations inhibit clearance of neutrophils by macrophages and may therefore prolong the presence of activated neutrophils in pustular psoriasis." (PMID 38448036, 2024). "Two genetic mutations associated with pustular psoriasis have been recently described: AP1S3 and MPO." (PMID 38448036, 2024).
rhinitis (3 papers, 2022 to 2026). An inflammation of the mucous membrane lining the nose, usually associated with nasal discharge. "Here, we introduce a multiscale material platform based on colloidal quantum dots (CQDs) for the construction of electrochemical immunosensors enabling the rapid detection of eosinophil cationic protein (ECP) and neutrophil myeloperoxidase (MPO), two clinically relevant biomarkers of rhinitis." (PMID 41660114, 2026). "The accurate MPO detection enabled by this biosensor can be combined with early ECP detection, which is significant for the precise diagnosis of the nature and degree of the local inflammation in rhinitis treatment." (PMID 36832021, 2023).
sarcoidosis (3 papers, 2020 to 2025). Sarcoidosis is a multisystemic disorder of unknown cause characterized by the formation of immune granulomas in involved organs. "Enriched genes including MPO (myeloperoxidase), CXCL11, IL1A, CXCL10, FCGR3B, IL1B, TTN (titin), BATF2, VIP (vasoactive intestinal peptide), TLR3, CCR2, TLR7, and CR1 wereclosely related to sarcoidosis." (PMID 38137330, 2023).
sarcopenia (3 papers, 2021 to 2025). Progressive decline in muscle mass due to aging which results in decreased functional capacity of muscles. "Inflammatory biomarkers such as C-reactive protein (CRP), granulocyte–monocyte colony-stimulating factor (GM-CSF), interferon-γ (IFNγ), interleukins (IL-6 and IL-8), myeloperoxidase (MPO), P-selectin, and tumor necrosis factor-α (TNF-α) may naturally be elevated in cases of acute sarcopenia." (PMID 39458423, 2024).
sexually transmitted infections (3 papers, 2020 to 2025). "However, myeloperoxidase (MPO) is a measure of neutrophils and is elevated in women with sexually transmitted infections (STIs)." (PMID 32723796, 2020).
synovitis (3 papers, 2016 to 2025). Inflammation of a synovial membrane. "Although myeloperoxidase activity, indicative of synovitis, was detectable using IVIS imaging in an adjuvant monoarthritis model (positive control), no sustained signal was observed following DMM." (PMID 26698846, 2016). "We report the first documented case of synovitis, acne, pustulosis, hyperostosis, and osteitis (SAPHO) syndrome in a Japanese male with positive serum myeloperoxidase antineutrophil cytoplasmic antibodies (MPO-ANCA)." (PMID 40497194, 2025). "We showed that BV and Col decreased the increase in MPO-positive cells and decreased MSU-induced synovitis in the ankle joint tissue of gouty rats." (PMID 34564665, 2021).
systemic sclerosis (3 papers, 2021 to 2024). A chronic disorder, possibly autoimmune, marked by excessive production of collagen which results in hardening and thickening of body tissues. "In fact, monospecific P-ANCA-positive patient cases with anti-MPO reactivity included one each with SLE, APS, RA and systemic sclerosis, whereas one patient with SS reacted with elastase and a SLE patient with lactoferrin." (PMID 34440897, 2021).
vaginitis (3 papers, 2012 to 2025). A non-infectious or infectious inflammatory process affecting the vagina. "We investigated the effects of the PRME extract and puerarin on MPO activity in the vaginal tissue of mice with GV-induced vaginitis." (PMID 39941110, 2025). "The activation of myeloperoxidase, prostaglandin E2, and nuclear factor-κB, and the expression of cyclooxygenase-2 were reduced by an intravaginal administration of PAA in the vaginitis mouse model." (PMID 38806600, 2024). "Numerous studies have reported that myeloperoxidase (MPO) activity is used as a biomarker for GV- and CA-induced vaginitis, indicating an increased accumulation of polymorphonuclear cells in the vaginal tissue of mice." (PMID 38806600, 2024).
acute monocytic leukemia (2 papers, 2021 to 2026). Acute monoblastic leukemia (AML-M5), is one of the most common subtypes of acute myeloid leukemia (AML) that is either comprised of more than 80% of monoblasts (AML-M5a) or 30-80% monoblasts with (pro)monocytic differentiation (AML-M5b). "CD68, lysozyme, and myeloperoxidase are the most sensitive immunohistochemical markers for detecting monoblasts (acute monocytic leukemia 5) or myelomonoblasts (acute monocytic leukemia 4), which account for the vast majority of leukemias at this age." (PMID 34449594, 2021). "The effect of MPO, PON1, and serums from the individuals with ASCVD and healthy individuals on cholesterol efflux of human acute monocytic leukemia cell line (THP-1 cells) was compared." (PMID 41704870, 2026).
AIDS (2 papers, 2017 to 2020). A syndrome resulting from the acquired deficiency of cellular immunity caused by the human immunodeficiency virus (HIV). "Furthermore, higher concentrations of some degranulation markers, including MPO, arginase I, and NGAL were reported in sera of patients with HIV infections; some of these proteins can contribute to T cell dysfunction, a hallmark of acquired immune deficiency syndrome (AIDS)." (PMID 28230780, 2017).
alcoholic cirrhosis (2 papers, 2018 to 2022). "A deficient release of MPO in decompensated alcoholic cirrhosis causes a decrease in neutrophils antimicrobial ability, as ROS production by MPO helps in killing the microorganisms in chronic diseases." (PMID 35681439, 2022). "However, a decrease in the antimicrobial capability of neutrophils occurred due to the deficient release of MPO in decompensated alcoholic cirrhosis." (PMID 35681439, 2022). "RIPK3 and MPO may serve as potential predictors for poor prognosis in patients with alcoholic cirrhosis." (PMID 30596105, 2018). "Importantly, RIPK3 and MPO may act as factors to predict poor outcomes in patients with alcoholic cirrhosis." (PMID 30596105, 2018). "The patients in our study all had end-stage alcoholic cirrhosis, and the results of our study between the relationship of the AHHS score and clinical parameters, MPO, or RIPK3 were not significant, suggesting the AHHS score may not be suitable for alcoholic cirrhosis." (PMID 30596105, 2018).
allergic dermatitis (2 papers, 2021 to 2025). "Serum MMP9 levels have previously been shown to be higher in adult asthmatic patients compared to controls and both MPO and MMP9 are upregulated in children with atopic dermatitis." (PMID 33722194, 2021).
Alpha-thalassemia (2 papers, 2020 to 2024). Alpha-thalassemia is an inherited hemoglobinopathy characterized by impaired synthesis of alpha-globin chains leading to a variable clinical picture depending on the number of affected alleles. "Such a modifying effect of alpha-thalassemia in MPO may provide a possible explanation for our findings of alpha-thalassemia and low levels of TG in SCD." (PMID 38265339, 2024). "Studies have shown that alpha-thalassemia has a modulatory effect on oxidative stress in SCA, likely attributed to a decrease in myeloperoxidase (MPO) activity." (PMID 38265339, 2024). "Our results suggest that alpha-thalassemia modulates oxidative stress in SCA, presumably because of a reduction in the MPO activity." (PMID 32937882, 2020). "Our work confirms the modulatory effects of alpha-thalassemia on oxidative stress in SCA, presumably by a reduction in the MPO activity." (PMID 32937882, 2020).
amnesia (2 papers, 2014 to 2018). Pathologic partial or complete loss of the ability to recall past experiences ( AMNESIA, RETROGRADE) or to form new memories ( AMNESIA, ANTEROGRADE). "Notably, the high levels of pro-inflammatory cytokines (TNF-α and MPO) and inflammatory mediator (NO) were detected in the brain of amnesia mice induced by scopolamine." (PMID 29755345, 2018).
anaphylaxis (2 papers, 2019 to 2025). An acute hypersensitivity reaction that occurs from exposure to an allergen. "MPO levels were 2.9-fold higher in moderate and 5 times higher in severe anaphylaxis." (PMID 39721985, 2025). "MPO levels were raised in all cases of anaphylaxis regardless of whether there was a detectable rise in histamine or tryptase." (PMID 39721985, 2025).
and mouth disease (2 papers, 2018 to 2026). "Salivary myeloperoxidase levels are dependent on two main factors: the natural migration of neutrophils into saliva and the inflammatory response of the mucous membranes in oral diseases." (PMID 41596237, 2026). "For example, increases in plasma MPO and S100A8/A9 levels have been reported in hand, foot, and mouth disease (HFMD) patients, and Andro-S was demonstrated to be clinically effective against HFMD by reducing fever and inflammation." (PMID 30174607, 2018).
aortic aneurysm (2 papers, 2024). A ruptured aneurysm located in the wall of the proximal portion of the descending aorta proceeding from the arch of the aorta. "It should be noted here again that the association of increased MPO plasma levels with aortic aneurysm, which has been documented in several studies, resulted from using healthy donors for comparison." (PMID 39766232, 2024).
Ascites (2 papers, 2025). Accumulation of fluid in the peritoneal cavity (between the layers of the peritoneum that lines the abdomen). "In addition, in our cohort, a high proportion of ascites-associated neutrophils exhibited MPO expression being associated with neutrophil extracellular traps (NETs)." (PMID 41221283, 2025). "APS enhanced the antioxidant capacity of tumor-bearing mice, specifically, APS reduced the levels of malondialdehyde (MDA), nitric oxide (NO), and myeloperoxidase (MPO), while increasing the activities of SOD, CAT, and GSH-Px by establishing a mouse ascites tumor model." (PMID 40143189, 2025).
autism spectrum disorder (2 papers, 2013 to 2022). A spectrum of developmental disorders that includes autism, and Asperger syndrome. "In a RCT, the effect of CM (average 500 ml, daily for 2 weeks) in 60 subjects with autism spectrum disorder (ASD) caused a significant increase in serum levels of GST and SOD, but decreased MPO." (PMID 35493477, 2022). "The present study aimed at evaluating the effect of camel milk on oxidative stress among subjects with autism spectrum disorders by measuring the levels of antioxidant enzymes: SOD, MPO, and GSH." (PMID 24069051, 2013).